RN7SL143P (RNA, 7SL, cytoplasmic 143, pseudogene)
Gene: Miscellaneous RNA gene on chromosome 16 (58,770,524 to 58,770,820, forward strand). Ensembl gene ENSG00000244003.
Homologues: Orthologues: chimpanzee Metazoa_SRP (99% identical), macaque Metazoa_SRP (83% identical). Paralogues in human: RN7SL2 (82% identical), RN7SL1 (82% identical), RN7SL3 (80% identical), RN7SL621P (80% identical), RN7SL479P (79% identical), RN7SL47P (79% identical), RN7SL127P (79% identical), RN7SL326P (79% identical), RN7SL786P (79% identical), RN7SL126P (78% identical), RN7SL45P (78% identical), RN7SL732P (78% identical), and 706 more.